SIRT4 (sirtuin 4)
Diseases named in the same sentence as SIRT4 in open-access papers (continued):
Sharing a sentence is not in itself a finding about the gene and the disease.
tumor (continued). "To detect whether SIRT4 plays a tumor-suppressive role through the modification of GLUD1 in PCa, we performed various rescue experiments." (PMID 35847357, 2022). "However, there is quite a consensus in the literature that HDAC4, HDAC7, HDAC9, SIRT2, and SIRT7 are upregulated in GC and seem to be pro-tumor factors, whereas SIRT4, SIRT5, and SIRT6, which are downregulated, seem to have a tumor suppressor function." (PMID 36358890, 2022). "In tumor-related studies, it has been proposed that SIRT4 is strongly correlated with glutamine metabolism, playing an important role in maintaining energy metabolism and contributing to the energy required for rapid tumor cell proliferation." (PMID 36376267, 2022). "Given its differential pattern of expression, it can be speculated that SIRT4 exhibits both tumor-suppressing and tumor-promoting effects." (PMID 36291902, 2022). "Additionally, low SIRT4 correlated with higher malignancy of GC, tumor growth (infiltration depth), metastases to successive lymph nodes, and a higher number in UICC classification of cancer staging." (PMID 36499440, 2022). "Simultaneously, we conducted several phenotypic experiments related to tumors to verify whether SIRT4 affects tumor progression." (PMID 35847357, 2022). "In addition, in the SIRT4-overexpressing group, the average tumor weight was also lower than that in the control group." (PMID 35847357, 2022). "Furthermore, SIRT4 expression was found to be even lower in lymph node metastases in comparison to respective primary tumor." (PMID 35356277, 2022). "Taken together, although not much studied, the current available data on the expression and function of SIRT4 in GC suggest that it might have tumor suppressor function in GC." (PMID 36358890, 2022). "The survival and proliferation of tumor cells depend on glutamine, and SIRT4 can inhibit the glutamate dehydrogenase activity by regulating its ADP-ribosyltransferase cofactor, thereby inhibiting glutamine metabolism and finally preventing tumor cell proliferation and inducing apoptosis." (PMID 35154350, 2022). "Notably, it is through the inhibition of glutamine metabolism that SIRT4 exhibits tumor suppressor effects in B Cell Lymphoma, 2014), colorectal cancer, and thyroid cancer." (PMID 36291902, 2022). "However, many findings point out the tumor suppressor role of this mitochondrial SIRT able to counter the gaining of malignant properties from cancerous cells, underlining that SIRT4 expression is lower in CRC compared to normal tissue." (PMID 35328633, 2022). "Based on the role of mitochondrial HBx in inducing oxidative stress and the tumor-suppressive function of SIRT4, both of which share the same mitochondrial localization, this study aimed to investigate the functional role of SIRT4 and its interaction with HBx in the development of HBV-related HCC." (PMID 33931611, 2021). "SIRT4 also exerts a tumor-suppressive role by prompting abnormal cells to spontaneous death." (PMID 34135317, 2021). "Relatively, SIRT4-mediated blockade of glutamine anaplerosis also could be a tumor suppressor mechanism." (PMID 34135317, 2021). "Taken together, our findings suggest that the tumor-suppressive role of SIRT4 is downplayed by HBx expression, which may be one of the tumorigenic properties of HBx." (PMID 33931611, 2021). "Therefore, SIRT4 silencing in macrophages prominently prompts macrophage-induced tumor development in vitro and in vivo." (PMID 33585187, 2020). "The evidence provided above suggests that SIRT4 is a tumor suppressor." (PMID 33585187, 2020). "Moreover, we collected twenty pairs of tumor and normal liver tissues from HCC male patients, and found that expression levels of SIRT1 (p = 0.002), SIRT2 (p = 0.01), and SIRT4 (p = 0.045) were significantly up-regulated in tumor tissues." (PMID 33093847, 2020). "Therefore, as far as it concerns the modulation of genome stability, Sirt4 plays a dual role in inhibiting and promoting tumor formation." (PMID 32373514, 2020).
tumor (continued). "In addition, SIRT4 overexpression led to tumorigenesis and inhibited tumor development in a xenotransplantation model using Tsc2−/− mouse embryonic fibroblasts (MEFs)." (PMID 33585187, 2020). "However, Lei and colleagues claimed that SIRT4 is involved in catabolism of branched-chain amino acids and promotes cell proliferation and tumor growth in PDAC by regulating BCAT2." (PMID 33585187, 2020). "Since we have confirmed miR-424-5p has a tumor promoting function in proliferation and migration of ESCC by targeting SIRT4, we speculate that there may be a close association between miR-424-5p and metabolic reprogramming of ESCC." (PMID 33033517, 2020). "In order to test whether ectopic expression of SIRT4 could succeed in altering the tumor-initiating frequency, we injected transformed MDA-MB-231 cells with serial dilutions into nude mice." (PMID 32863939, 2020). "For its capability to inhibit glutamine catabolism and for the modulation of genome stability in cancer cells in response to different DNA-damaging conditions, Sirt4 is proposed as either a mitochondrial tumor suppressor or a tumor-promoting protein in a context-dependent manner." (PMID 32373514, 2020). "Therefore, SIRT4 deletion-dependent tumor biology is dependent mainly on activation of AMPKα stimulated by AMP/ADP." (PMID 33585187, 2020). "Moreover, Haigis and colleagues reported that SIRT4 functions as a tumor suppressor to regulate the cellular metabolic response to DNA damage by suppressing mitochondrial glutamine metabolism." (PMID 33117704, 2020). "Using IHC analyses and flow cytometry (FCM), two interesting phenomena were discovered: (i) increased infiltration of tumor-associated macrophages (TAMs); (ii) a higher proportion of M2/M1 macrophages in the tissue around the HCC in the group of low SIRT4 expression." (PMID 33585187, 2020). "In addition, SIRT4 expression was negatively correlated with the pathologic grade, depth of tumor invasion, number of positive lymph nodes, and International Union Against Cancer stage." (PMID 33585187, 2020). "Many studies have established a tumor-suppressive role of SIRT4 in cancer." (PMID 30952833, 2019). "Importantly, SIRT4 can regulate insulin secretion and has tumour suppressor activity via modulation of glutamate dehydrogenase." (PMID 31744516, 2019). "Furthermore, total protein and RNA were extracted from fresh HCC tissues and matched peritumour tissues, and western blot and qRT-PCR assays confirmed that SIRT4 was downregulated in tumour tissues compared with peritumour tissues." (PMID 31744516, 2019). "It seems that SIRT4 plays a tumour-suppressing role mainly in peritumour tissues." (PMID 31744516, 2019). "Similarly, tumour weight in the control TAM group was less than that in the SIRT4-knockdown M2-like TAM group." (PMID 31744516, 2019). "Thus, SIRT4 silencing in macrophages significantly promoted macrophage-induced tumour development both in vitro and in vivo." (PMID 31744516, 2019). "As a gene related to energy metabolism, SIRT4 acts as a tumor suppressor in many cancers." (PMID 31573734, 2019). "Indeed, SIRT4 expression is upregulated by DNA damage and is downregulated in many types of human tumor tissues and cells." (PMID 30666234, 2018). "SIRT4 has also been identified as a mitochondrial-localized tumor suppressor." (PMID 30666234, 2018). "Therefore, as a glutamine steward, SIRT4 acts as a necessary component of the DNA damage response pathway that manages the metabolic blockade of glutamine metabolism, the cell cycle, and tumor suppression." (PMID 30666234, 2018). "Overexpression of SIRT4 decreases cell growth, transformation and development of tumor." (PMID 30666234, 2018). "Additionally, a role for SIRT4 in response to genotoxic stress and tumour suppression is discussed in the context of SIRT4 as a regulator of mitochondrial glutamine metabolism." (PMID 29059204, 2017). "The inhibitory role of SIRT4 on GDH makes SIRT4 as a tumor suppressor." (PMID 28197299, 2017).
tumor (continued). "In addition, we also observed that a possible tumor repressor, SIRT4, was demonstrated to negatively mediate CtBP-regulated glutaminolysis." (PMID 25633289, 2015). "As SIRT4-repressed glutaminolysis inhibited cancer cell growth, our elucidation that SIRT4 acts as a target gene of CtBP further strongly supports the view that CtBP can be a potential target of tumor therapeutic strategy." (PMID 25633289, 2015). "Combined, these observations strongly suggest that SIRT4 has tumor-suppressive effects and that its downregulation may serve to facilitate the progression of several human cancers." (PMID 25332769, 2014). "Furthermore, overexpression of SIRT4 opposes cell proliferation, transformation, and tumor progression as shown in an in vivo murine model." (PMID 25332769, 2014). "However, it could serve as a tumor suppressor when it is overexpressed in the cancer cells expressing high levels of SIRT4 such as α2δ1+ HCC TICs, as demonstrated herein." (PMID 40384857, 2025). "Moreover, SIRT3 and SIRT4 have been shown to inhibit tumor cell proliferation." (PMID 41011152, 2025). "This downregulation implies that reduced SIRT4 expression could contribute to tumor development." (PMID 40710366, 2025). "Similarly, SIRT4 acts as a tumor suppressor by regulating glutamine metabolism." (PMID 41471349, 2025). "The finding that low and high doses of exogenous acetyl-CoA had distinguishable roles in the determination of H3K27ac level and stemness of HCC TICs promoted us to hypothesize that the role of SIRT4 in tumor, which determined the amount of acetyl-CoA, might be dependent on its levels in the cells." (PMID 40384857, 2025). "Interestingly, SIRT4 not only acts as a tumor suppressor, but also promotes tumor progression." (PMID 38773972, 2024). "Thus, the extra-mitochondrial function of SIRT4 on C-RAF-MAPK signaling may provide a novel control mechanism for tumor suppression." (PMID 38499327, 2024). "Notably, SIRT4's function extends beyond metabolic regulation, implicating its involvement in diverse cellular processes, including insulin secretion, fatty acid oxidation, and tumor suppression." (PMID 38773972, 2024). "Moreover, tumor progression is delayed in xenograft models with SIRT4 overexpression." (PMID 38773972, 2024). "Therefore, depletion of SIRT4 expression reversed the anti-tumor effect of WDR79." (PMID 36712589, 2023). "Therefore, the role of SIRT4 in a specific type of tumor needs to be studied specifically." (PMID 37301821, 2023). "Recent research suggests that SIRT4 may work as both a tumor suppressor gene and an oncogene." (PMID 35842463, 2022). "This proposed axis of SIRT4-dependent inhibition of survivin and retention of cytoplasmic cyclin B1 in the suppression of tumor cell cycle progression and induction of apoptosis could shed light on the development of therapeutic targets against HCC tumorigenesis." (PMID 33931611, 2021). "Thus, stress-induced SIRT4 may exert its role as tumor suppressor through mitochondrial as well as extramitochondrial functions, the latter associated with its localization at the mitotic spindle apparatus." (PMID 32846968, 2020). "Thus, we propose that SIRT4 may exert its cell cycle inhibitory and tumor suppressor function through both mitochondria, i.e., bioenergetics-dependent, and mitochondria-independent, i.e., centrosome/mitotic spindle apparatus-linked mechanisms." (PMID 32846968, 2020). "Recent overviews of the literature revealed that SIRT4, although first described as a metabolic tumor suppressor, may display both tumor suppressor and oncogenic/cancer promoting activities, depending on the tumor type and checkpoint activating conditions." (PMID 32846968, 2020). "Moreover, SIRT4 has a tumour-suppressive activity by inhibiting mitochondrial glutamine metabolism." (PMID 31447696, 2019). "In addition, SIRT4 can inactivate glutamate dehydrogenase to inhibit tumour formation." (PMID 31744516, 2019).
tumor (continued). "Furthermore, SIRT4 suppresses tumour growth by repressing glutamine metabolism." (PMID 30356832, 2018). "Thus, SIRT4 inhibits mitochondrial glutamine metabolism, suggesting that it could act as a tumor suppressor." (PMID 25085992, 2014). "Finally, multiple human tumor types show reduced SIRT4 levels." (PMID 25085992, 2014). "The tumorigenicity of the α2δ1+ subpopulations was dramatically retarded following SIRT4 knockdown, as evidenced by the decrease in both the TIC frequencies and formed tumor sizes." (PMID 40298941, 2025). "While SIRT1, SIRT2, and SIRT6 can assume opposite functions in relation to the tumor context, SIRT3, SIRT4, and SIRT7 tend to function more in favor of tumors." (PMID 41425553, 2025). "Independently, SIRT4 also inhibits the MEK/ERK/c-Myc pathway, reducing glutaminase expression and impeding proliferation and metastasis, reinforcing its anti-tumor role." (PMID 41471349, 2025). "Conversely, SIRT2, SIRT4, and SIRT6 generally exhibit tumor-suppressive functions by inducing apoptosis, inhibiting invasion, and counteracting oncogenic signaling." (PMID 40710366, 2025). "The varied roles of SIRT3, SIRT4, and SIRT5 in metabolic adaptation and cancer are outlined, emphasizing their tumor suppressor or oncogenic nature." (PMID 38331199, 2024). "SIRT3 and SIRT4 suppress oncogenic pathways by regulating cancer metabolism, while SIRT2 and SIRT6 influence tumor aggressiveness and androgen receptor sensitivity, with SIRT6 promoting metastatic potential." (PMID 39796040, 2024). "In contrast, tumor-suppressive Sirtuins like SIRT3 and SIRT4 counteract these processes by reprogramming hypoxia-driven oncogenic pathways." (PMID 39682281, 2024). "Among the sirtuins, SIRT1, SIRT3, SIRT4, and SIRT6 have been identified as significant targets for anti-tumor treatments; SIRT4 has been proposed as a tumor-suppressor protein, reducing glutamine entry into mitochondria in response to DNA damage." (PMID 39195514, 2024). "In PCa models, SIRT4’s inhibition of glutamate dehydrogenase 1 (GDH1), a key enzyme in glutamine metabolism, was observed to curb metabolic pathways essential for tumor proliferation." (PMID 39796040, 2024). "SIRT4 expression in peritoneal tissues was positively correlated with patient survival and dramatically downregulated in HCC tumour." (PMID 39320855, 2024). "The SIRT4 binds to HIF-1α in a protein–protein interaction and directly inhibits HIF-1α expression, thereby blocking HIF-1α/HO-1-mediated tumor cell growth." (PMID 39876842, 2024). "Knockout of SIRT4 in CRC cells increased proliferation, migration, and invasion, confirming its tumor-suppressive effects." (PMID 38773972, 2024). "Studies have shown that the expression of SIRT2, SIRT3, SIRT6, and SIRT7 is increased in tumor-stage 1-4 subgroups, SIRT1 expression is increased in tumor-stage 1, and the expression of SIRT4 is decreased." (PMID 37096064, 2023). "In conclusion, our study shows that SIRT4 is involved in the development of BLCA and that SIRT4 acts as a tumor suppressor in BLCA and is a potential prognostic marker and therapeutic target." (PMID 37301821, 2023). "In the present study, we determined that SIRT4 was down-regulated in PDAC, serving as a tumor suppressor." (PMID 36209169, 2023). "Sirtuins, a family of orthologues of yeast silent information regulator 3 (SIRT3), 4 (SIRT4) and 5 (SIRT5) are important tumor suppressor genes located in mitochondria." (PMID 36809279, 2023). "The decreased expression levels of SIRT2, SIRT4, and SIRT5 were correlated with advanced tumor stages." (PMID 35136826, 2022). "In terms of KAT5, SIRT4, SIRT6 and SIRT7, these four genes demonstrated higher expression in tumours than in adjacent tissues." (PMID 36308411, 2022). "Inhibition of methionine metabolism by SIRT4 synergizes with sorafenib, thereby retarding the growth of HCC tumour by disrupting nucleotide metabolism and redox balance." (PMID 36371321, 2022).
tumor (continued). "We examined the expression of SIRT4 in the 9 normal liver biopsies and 30 pairs of HCC tumors and their adjacent non-tumor counterparts." (PMID 33931611, 2021). "On the basis of our study, VHL, SIRT4, HIF-1α, and HO-1 were genes related to a few tumor-related biological processes, including metabolism, cancer development, and cellular stress response." (PMID 34135317, 2021). "However, a few recent studies have demonstrated that Sirt4 can also be upregulated in some tumors and can exert oncogenic properties by regulating the stress responses of cancer cells and preparing them to gain selective advantages, including resistance to anti-tumor treatments." (PMID 32373514, 2020). "Moreover, Sirt4 has been indicated as a mitochondrion-localized tumor-suppressor protein that, like other sirtuins, may also act as an oncoprotein depending on the specific tumor type, stage, and overall biological context." (PMID 32373514, 2020). "The relationship between mRNA expression levels of SIRTs and different tumor stages of OC were also analyzed, and they were all significantly upregulated in stage II except for SIRT2 and SIRT4." (PMID 31572453, 2019). "Statistical analysis revealed that the expression of SIRT4 was positively correlated with the expression of KLF4 in the two cohorts, and both SIRT4 and KLF4 expression were decreased in tumor tissues." (PMID 30952833, 2019). "A family of orthologues of yeast silent information regulator 3 (SIRT3), 4 (SIRT4) and mitochondrial tumor suppressor 1 (MTUS1) are important mitochondrial tumor suppressor genes which play an important role in the progression of multiple cancers." (PMID 26785117, 2016). "A study examining the correlation between sirtuin expression and treatment outcomes found that SIRT4 and SIRT6 had significant prognostic value for both overall survival and progression-free survival, suggesting their potential roles as tumor suppressors in ovarian cancer." (PMID 41471349, 2025). "SIRT4 depletion promotes HCC tumour development through the AMPKα/mTOR pathway, while overexpression of SIRT4 induces G2/M cell cycle arrest and apoptosis, leading to tumour suppression." (PMID 40136715, 2025). "SIRT4 significantly inhibits glutamine metabolism by ADP-ribosylating glutamate dehydrogenase, thereby limiting the supply of energy and materials required for rapid proliferation in tumor cells." (PMID 39944690, 2025). "Even though the effects of SIRT3 may be specific to the types of tumours, upregulation of both SIRT3 and SIRT4 is currently being pursued as a potential strategy to improve cancer treatment outcomes." (PMID 38369747, 2024). "Another report suggests that SIRT4 is a downstream target of UHRF1 (ubiquitin-like with plant homeodomain and ring finger domains 1), an epigenetic modifier known to mediate the silencing of tumor suppressor genes." (PMID 39682281, 2024). "Meanwhile, SIRT4, as a downstream target of the epigenetic regulator UHRF1, antagonizes the HIF-1α-mediated transcription of glycolytic genes, thereby inhibiting glycolysis, tumor proliferation, and metastasis." (PMID 39682281, 2024). "Using a xenograft tumor model in nude mice, we also observed that the changes in AMPK expression could reverse the effect of SIRT4 expression on the tumorigenic ability of PDAC cells." (PMID 36209169, 2023). "As a tumor with high malignancy and poor prognosis, there are no studies on the relationship between SIRT4 and BLCA." (PMID 37301821, 2023). "SIRT4 is an important member of the SIRT family, a class of highly conserved nicotinamide adenine dinucleotide (NAD+)-dependent deacetylases, and numerous studies have demonstrated the implication of SIRTs in tumor metastasis." (PMID 36209169, 2023).